CCND1 (cyclin D1)
Diseases named in the same sentence as CCND1 in open-access papers (continued):
Sharing a sentence is not in itself a finding about the gene and the disease.
tumor (continued). "Consistent with gene expression analysis and immunohistochemical staining, immunoblot analysis revealed that p-STAT3, p-P65, Bcl-2, Bcl-xL and cyclin D1 levels in tumor tissues from KI mice were dramatically increased." (PMID 38607004, 2024). "Accordingly, 1,25(OH)2D3 reduced the expression of β-catenin target genes associated with tumour progression such as MYC (Myelocytomatosis) and CCND1 (encoding Cyclin D1)." (PMID 39494323, 2024). "NF-κB promotes the expression of multiple genes that contribute to tumor progression, such as cyclin D1, c-Myc, BCL2, snail, vimentin, and MMP2/3/9." (PMID 39336822, 2024). "We have identified a potential gene expression signature—Trp53bp1, Bax, Cyclin D1, p21, and Nanog—that influences tumor response." (PMID 39594660, 2024). "Meanwhile, the EZH2-mediated target gene CCND1 was upregulated in the tumor; CCND1 amplification is particularly common in ER-positive tumors and is associated with reduced survival in these patients." (PMID 38254989, 2024). "NFκB facilitates tumor cell survival, proliferation, and angiogenesis by regulating the expression of target genes such as cyclin D1, IL6, BCLXL, BCL2, XIAP, and VEGF." (PMID 39203892, 2024). "The activation of AR increases the expression of downstream targets like cyclin D1, which drives cell cycle progression and tumor growth." (PMID 39725665, 2024). "Amplification of or mRNA overexpression of CDK4, CDK6 and/or cyclin D1 was observed in 16% of tumours." (PMID 38612869, 2024). "In BC, PLK1 signalling has been shown to cooperate in ER‐dependent gene transcription, and its genetic or pharmacologic inhibition led to G2/M arrest in TNBC cell lines and to tumour shrinkage in CCND1‐driven PDX models of acquired palbociclib resistance." (PMID 38264947, 2024). "Hormone receptor‐positive, HER2‐negative (HR+/HER2−) tumours largely rely on oestrogen receptor (ER) signalling and downstream cyclin D1 (CCND1) to drive cell cycle progression through the G1/S checkpoint." (PMID 38264947, 2024). "The frequent genomic alterations in CDKN2A and CCND1 in HPV− clinical HNSCC cases suggest that there is a strong rationale to target CDK4/6 to inhibit tumor progression in HNSCC." (PMID 38954773, 2024). "Compared with MSN–BSA–NC, MSN–BSA–Anta and MSN–BSA–NC‐131I both inhibited tumour growth with reduced tumour volumes and decreased Ki67 as well as cyclin D1 levels." (PMID 38797942, 2024). "Further, downregulation of cyclin D1 in tumour tissues suggested that oral paclitaxel induced cell cycle arrest in tumour tissues in-vivo." (PMID 38172758, 2024). "Since Cyclin D1 is a direct transcriptional target of estrogen, it has been reported that ER+ tumor cells are particularly dependent on CDK 4/6 activation in cell proliferation." (PMID 38957324, 2024). "Downregulation was observed for the genes CCNG2 (−9.0-fold), CCND1 (−5.84-fold), TFDP1 (−5.84-fold), CDC34 (−5.14-fold), and HUS1 (−4.52-fold), which are normally linked to the development of various tumor types when overexpressed." (PMID 39337305, 2024). "Clinical studies suggest clear correlations between increased cyclin D1 expression and aggressive tumor phenotypes in cSCCs." (PMID 39062630, 2024). "Oncogenic signaling pathways result in uncontrolled cell cycle progression and tumor growth through the increased cyclin D1 expression (encoded by CCND1) and/or inhibition of cyclin D1 degradation." (PMID 39062630, 2024). "Pre- and post-treatment tumor samples were analyzed for fold changes in Ki-67, cyclin D1, p27, and cleaved caspase-3 (CC3) expression." (PMID 39273534, 2024). "This decrease in tumor weight is primarily due to Bay’s effects on inhibiting the expression of genes regulating the cell cycle and cell proliferation, including CCND1, E2F1, CKS2, and Ki67." (PMID 38994944, 2024). "The MYC family of oncogenes, including MYC and MYCN, promotes tumor growth and metastasis by upregulating key cell cycle genes, such as CCND1." (PMID 39410541, 2024).
tumor (continued). "MiR-15a-5p, as a suppressor of tumour formation, promotes apoptosis and inhibits tumour growth by targeting specific oncogenes, such as Bcl-2, CcnD1, Mcl1, and Wnt3A." (PMID 38698968, 2024). "Our analysis revealed that PACA 1 and 2 tumours exhibit comparable levels of cyclin D1 expression, which is higher than that of the PACA 3 subtype." (PMID 39738026, 2024). "We also showed that this was associated with changes in the tumor immune microenvironment and tumor-specific downregulation of Wnt target genes’, c-myc and cyclin D1, expression." (PMID 38542253, 2024). "The results confirmed that a significant downregulation of cyclin B1, cyclin D1, and cyclin E1 in four tumor cell lines were stimulated with H9." (PMID 39458945, 2024). "Aqueous extract obtained from Scutellaria baicalensis resulted in a reduction in the expression of MMP-2 by downregulating Cyclin D1, thus hindering the growth and invasion of tumor cells." (PMID 39161904, 2024). "Accumulation of β-catenin in the nucleus also induces transcription of both c-Myc and cyclin D1, thus contributing to tumor growth and progression." (PMID 39337385, 2024). "Cyclin D1 known to facilitate tumor cell proliferation and push the cell cycle from the G1 phase to the S phase." (PMID 39048945, 2024). "Since FIRRE overexpression promotes tumor growth, we examined the status of cyclin D1 expression for a mechanistic relationship." (PMID 38556083, 2024). "Additional studies highlighted an importance of cyclin D1 levels in resistance of cancer cells to PI3Kα inhibitors and revealed a synergistic anti-tumor effect upon combined targeting with CDK4/6 inhibitors." (PMID 38286037, 2024). "The reduced cyclin-D1 expression in tumour tissues suggests that oral paclitaxel exerts a therapeutic effect by targeting cyclin-D1 in CMGC." (PMID 38172758, 2024). "Most of the cyclin D1 positive cases had pT2 tumors, with the majority being grade 2 tumors and tumor size of >2 to </= 5 cm." (PMID 40034931, 2024). "Modulation of proteins such as ER and cyclin D1 and/or whole transcriptome gene expression analysis on tumor paired biopsies is ongoing to assess how PF-07248144 regulates the tumor microenvironment and specific signaling pathways." (PMID 38824244, 2024). "High expression of Cyclin D1 drives uninhibited cell proliferation and promotes tumor growth, thus, Cyclin D1 plays a central role in the pathogenesis of cancer." (PMID 39605083, 2024). "The genomic profiles of both tumor lesions were consistent with HR-NB and showed several persistent segmental alterations, including 3p and 11q deletion, gain of CCND1, 7q, 17q, and an alteration at 5p indicating TERT juxtaposition." (PMID 39324010, 2024). "Overexpression of β-catenin in tumor tissues then activates downstream target genes such as c-Myc and cyclin D1, which encourage the proliferation and survival of cancer cells." (PMID 39554609, 2024). "In vivo, K1 cells overexpressing miR‐31 gave rise to dramatically larger tumours in xenograft models with increased cyclin D1 staining, representing accelerated cell cycle." (PMID 38797942, 2024). "Cyclin D1 and p16INK4A proteins are involved in cell proliferation via regulation dependent on the Rb protein, and disturbances in this regulation can lead to tumor development." (PMID 39684268, 2024). "Specifically, CCND1 knockdown partially reversed the stimulative effect of MAT1A overexpression on tumor growth in mice." (PMID 39438468, 2024). "Luminal tumours also frequently harbour activating mutations in the PI3K signalling pathway and CCND1 amplifications." (PMID 38264947, 2024).
tumor (continued). "Upregulated NAP1L1 plays a pro-tumorigenic role by recruiting HDGF to interact with c-Jun, thereby upregulating the expression of CCND1 and promoting the proliferation of tumour cells." (PMID 38538582, 2024). "In our present study, the TCF12–MALAT1 alliance is significantly associated with a β-catenin-independent induction of cyclin D1 gene expression, which acts as a risk factor for CRC patient mortality, associated more with tumor recurrence than with metastasis." (PMID 39768127, 2024). "Only in the HCC1806 TNBC tumor line did we observe consistent down-regulation of Cyclin D1 for all culture conditions (i.e., monoculture and combinations)." (PMID 38386805, 2024). "AKT also accelerates cell cycle progression by regulating cell cycle control factors such as p21 and Cyclin D1, further driving tumor cell proliferation." (PMID 39769140, 2024). "Specifically, the expression levels of tumor proliferation and angiogenesis protein CCND1 and VEGFC were upregulated by STOML2 overexpression." (PMID 38214751, 2024). "The tumours harvested from WD-fed mice showed an increased level of Ki67 and of Cyclin D1 mRNA (Ccnd1), two proliferation markers whose expression is usually enhanced in HCC tissues." (PMID 38824560, 2024). "The activation of canonical FGFR downstream MAPK signaling pathways promote tumor growth through CCND1 upregulation." (PMID 38553760, 2024). "In the tumour tissue analysis, decreased cyclin-D1, increased TUNEL-positive cells, and decreased CD31-positive cells were observed in the paclitaxel group." (PMID 38172758, 2024). "In cervical cancer, miR-146a also has an increased level and a tumor-promoting role, which it exerts by inhibiting IRAK1 and TRAF-6 (TNF-receptor-associated factor 6) and stimulating Cyclin-D1." (PMID 39057062, 2024). "The IL‐6/STAT3 pathway involves key proteins like Bcl‐2 and Bax, crucial for tumour cell apoptosis and Cyclin D1 and CDK‐4, which contribute to tumour cell proliferation." (PMID 39495702, 2024). "Consistently, Ki67, MMP2, MMP9, c-Myc, β-catenin, CDK4, CDK6, and Cyclin D1 protein levels in tumor tissues were significantly decreased by SAMD5 overexpression but partially increased by PLK1 overexpression." (PMID 39524172, 2024). "The histopathological and molecular features of the tumor, including mutations in ABL1, CCND1, CSF1R, FGFR4, KDR, and MALAT1-GLI1 fusion, are elucidated and discussed in the context of diagnostic, prognostic, and therapeutic considerations." (PMID 38732067, 2024). "Tumor cells with dysregulated Fbxo4-cyclin D1 show increased Gln uptake, leading to a paradox of elevated Gln consumption but compromised energy production due to mitochondrial dysfunction." (PMID 38474224, 2024). "CCL5, a ligand of CCR5, is a product of cancer itself and its microenvironment, using the mTOR pathway through the regulation of cyclin D1, c-Myc, and Dad-1 expression to enhance tumor growth." (PMID 39329983, 2024). "Both miR-15a and miR-16-1 expression inversely correlated with the expression of cyclin D1, and let-7a has been shown to function as a tumor suppressor in multiple tissues." (PMID 39336822, 2024). "And, we also confirmed that Erianin can block the cell cycle of DDP-resistant LUAD cells in the S and G2/M phases, and down-regulate the expression of Cyclin D1 protein to exert its anti-tumor effects." (PMID 39605083, 2024). "We previously reported that FXR promotes NSCLC tumor growth via upregulating CCND1 transcription and remodeling an immunosuppressive microenvironment." (PMID 38360812, 2024). "NF-kB can induce cell proliferation and promote tumor formation by activating proto-oncogenes such as C-myc and cyclin D1." (PMID 39314753, 2024).
tumor (continued). "This study shows didox downregulates an element of the cell cycle checkpoint, cyclin D1, accompanied by a reduction in NF-κB activity in vitro and tumor growth inhibition of palbociclib-resistant ER positive breast cancer tumor growth in vivo." (PMID 38473336, 2024). "STAT1/ STAT2 has a large number of target genes, including NO, BCL-2, p21, and CCND1, which all participate in pro-apoptotic and cell-cycle regulation, and act as tumor suppressors in various cancers." (PMID 38191598, 2024). "Immunohistochemistry showed that the tumor cells were positive for Cyclin D1, smooth muscle actin (SMA), and Desmin." (PMID 39469368, 2024). "Several studies have demonstrated changes in cyclin D1 expression, both in the early stage and along tumor progression, in different types of cancers, including breast, head and neck, prostate and renal cell carcinoma and PC." (PMID 38742684, 2024). "A trend of decreased mOS was observed in relation to Cyclin D1 overexpression and normal expression, with mOS of 20.09 vs. 33.23; p = 0.056, while high PDGFRβ expression in the tumor stroma resulted in survival rates of 24.90 vs. 48.36 months; p = 0.068." (PMID 38791897, 2024). "Beyond that, western blot analysis exhibited that the protein levels of METTL14, AOC1, Cyclin D1, Bcl-2, and N-cadherin were clearly lower in tumor tissues derived from sh-METTL14-transfected C666-1 cells." (PMID 38956710, 2024). "The protein and mRNA levels of cell proliferation marker Cyclin D1 were lower in the tumor tissues of Postn-/-Rag1-/- mice than those in Postn+/+Rag1-/- mice." (PMID 38773979, 2024). "This approach enabled us to identify several compounds exhibiting strong binding affinities to CCND1, thereby suggesting their potential as promising candidates for developing anti-tumor drugs." (PMID 38957406, 2024). "Cyclin D1, a prevalent oncogene overexpressed in OSCC, has strong associations with clinical indicators such as tumor-node-metastasis (TNM) stage, high histological grade, and poor prognosis." (PMID 38698370, 2024). "In tumor therapy, D609 inhibits the growth of neural progenitor cells by reducing ERK‐mediated cyclin D1 expression with potential therapeutic effects in preventing tumor stem cell growth." (PMID 39692711, 2024). "Analysis of the mechanism using RNA sequencing demonstrate higher levels of GLI2 targets, particularly tumor growth–promoting genes, including Ccnd1, N-Myc, and Bcl2, in KrasG12D mutant cells." (PMID 38896052, 2024). "p-STAT3 promotes tumour growth mainly by promoting the transcription of cell proliferation and survival genes, such as c-Myc, cyclin D1 and Bcl-xL." (PMID 38504172, 2024). "Forced expression of miR-29 in RMS cell lines slowed down cell proliferation and inhibited tumor growth, increased Cyclin D1 (CCND1) and reduced CDKN1A expression, and induced cell cycle arrest and terminal muscle differentiation." (PMID 37345159, 2023). "In conclusion, evidence suggest that CCND1 expression is upregulated in HNSC and is associated with tumor development." (PMID 37481637, 2023). "The combination of KLK2 and ARA70 can reduce G1 arrest of tumor cells and promote tumor proliferation by regulating p21/cdk2/cyclin D1 signaling pathway." (PMID 37593117, 2023). "The expressions of MMP-9, VEGF, Bcl-2, and Cyclin D1, involved in tumor progression, were found to increase in the radiation-alone group, but they decreased in the Rh2-alone and combination groups." (PMID 37764996, 2023). "Previously, we showed an anti-tumor effect of miR-195 in HNSCC via the inhibition of Cyclin D1 and BCL-2 expression." (PMID 38136338, 2023). "In contrast, DYRK2 overexpression in Huh1 and PLC/PRF5 cell lines using an adenoviral vector suppressed cyclin D1 and D2 and c-Myc expression, tumor growth, and colony formation." (PMID 37886981, 2023). "Our results suggest that the overexpression of E2F-cyclin D1 co-stimulating regulatory loops can enhance cell cycle progression, potentially leading to uncontrolled tumor cell growth." (PMID 36849756, 2023).
tumor (continued). "The pivotal role of STAT3 in tumor development stems from its capacity to regulate the transcription of genes involved in various key processes, such as the cell cycle (CCND1, CCNE1), metabolism (OCT1, HIF1A), and cell survival (BCL2, BCLXL, and HSP70)." (PMID 37474926, 2023). "Compared to HES1 (−) tumors, expression levels of Ki67 (p = 0.0268), RB1 (p = 0.0271) and Cyclin D1 (p = 0.0487) were all significantly upregulated in the HES1 (+) tumor cells." (PMID 37749297, 2023). "Proliferation-related proteins P-STAT3 and Cyclin D1 in tumor tissues were examined by Western blot analysis." (PMID 37640735, 2023). "Regarding cyclin D1 gene expression, it showed significant upregulation in the tumor tissue by 1.8 folds compared to the normal control group." (PMID 36905557, 2023). "CCND1 is a D-cyclin and serves as an effector gene promoting tumor progression in a variety of cancers including GC." (PMID 37340423, 2023). "As proto-oncogenes, cyclin D1 and c-Myc play key roles in tumor cell growth, migration and invasion." (PMID 37773165, 2023). "Cyclin D1 overexpression leads to dysregulated cell proliferation, as well as malignant tumor transformation and development, including PTC." (PMID 37427143, 2023). "In the conventional tumor area, cyclin D1 and p16 were frequently expressed in more than half of the tumor cells, and membranous β-catenin expression was preserved." (PMID 38002025, 2023). "In situ mantle cell neoplasm/neoplasia represents an incidental finding characterized by colonization of mantle zone of B-cell follicles by neoplastic B cells carrying the IGH::CCND1 fusion and overexpressing cyclin D1 at immunohistochemistry." (PMID 36460764, 2023). "SIX1 promoted cyclin D1 transcription in rhabdomyosarcoma cells, leading to tumor initiation, and SIX1 also facilitated BC cell proliferation via inducing cyclin A expression." (PMID 36750914, 2023). "WNT1 not only accelerates the proliferation of tumors by upregulating c-Myc, but also promotes the tumor malignant proliferation and angiogenesis by inducing the expression of target genes such as Cyclin D1, VEGF-A, and matrix metalloproteinase 7 (MMP7)." (PMID 37486552, 2023). "Evidence has been presented demonstrating that CCND1 participates in the tumor-suppressive action of the E3 ligase adaptor, autophagy and beclin 1 regulator 1 to limit the growth of UVM cells." (PMID 37076452, 2023). "CCND1, a positive cell cycle regulator, was frequently deregulated in tumor and was an indicator of cancer phenotype and disease development." (PMID 37056778, 2023). "Previous research on breast cancer has demonstrated that the interaction between filamin A and cyclin D1/cyclin-dependent kinase 4 can influence the tumor’s ability to migrate and invade." (PMID 36821071, 2023). "The non-tumour portion of Atf4Δhep livers showed elevated cyclin-D1 (CCND1), mouse double minute 2 homologue (MDM2), connective tissue growth factor (CTGF), and DR5 mRNAs, but reduced FGF21 mRNA." (PMID 36996941, 2023). "Our present data supported the function of RNU12 in inhabiting GC tumor progression through suppressing the cell growth, migration, invasion, as well as the proliferative ability expression with CCND1, PCNA, N-cadherin, E-cadherin, Vimentin and BCL-2." (PMID 37160927, 2023). "Down-regulated genes belong to the class of oncogenes (Akt1, Ccnd1, Myb, and Src) and tumor suppressors (Brca1, Brca2, and Mlh1)." (PMID 37297299, 2023). "This pRB-dependent control of cell proliferation is considered the “canonical” function of Ccnd1 and it has been reported as very relevant in tumour proliferation." (PMID 37684532, 2023).